SRD5A3 (steroid 5 alpha-reductase 3)
Description:
Plays a key role in early steps of protein N-linked glycosylation by being involved in the conversion of polyprenol into dolichol. Acts as a polyprenal reductase that mediates the reduction of polyprenal into dolichal in a NADP-dependent mechanism. Dolichols are required for the synthesis of dolichol-linked monosaccharides and the oligosaccharide precursor used for N-glycosylation. Also able to convert testosterone (T) into 5-alpha-dihydrotestosterone (DHT).
Synonyms: S5AR 3; SRD5A2L; FLJ13352; SRD5A2L1; CDG1P; CDG1Q; KRIZI; S5AR
Tractability: Small molecule: an approved drug acts on it; it belongs to a druggable protein family. Antibody: UniProt predicts a signal peptide or a membrane-spanning region; the Human Protein Atlas places it where antibodies can reach. PROTAC: ubiquitination databases record sites on it.
Gene: Protein-coding gene on chromosome 4 (55,346,213 to 55,373,100, forward strand). Ensembl gene ENSG00000128039.
Subcellular location: Endoplasmic reticulum membrane
Subcellular location (Human Protein Atlas): Cytosol; Plasma membrane
Pathways (Reactome):
Disease: Defective SRD5A3 causes SRD5A3-CDG, KHRZ
Metabolism: Androgen biosynthesis
Metabolism of proteins: Synthesis of dolichyl-phosphate
Gene Ontology:
Molecular function: 3-oxo-5-alpha-steroid 4-dehydrogenase (NADP+) activity; oxidoreductase activity, acting on the CH-CH group of donors, NAD or NADP as acceptor; polyprenal reductase activity; 3-oxo-5-alpha-steroid 4-dehydrogenase activity; oxidoreductase activity, acting on the CH-CH group of donors
Biological process: dolichyl monophosphate biosynthetic process; androgen biosynthetic process; dolichol-linked oligosaccharide biosynthetic process; lipid metabolic process
Cellular component: endoplasmic reticulum; endoplasmic reticulum membrane
Genetic constraint (gnomAD): Loss-of-function variants: 24 observed, 33.61 expected, observed/expected ratio (o/e) 0.71, 90% interval 0.52 to 1. The upper end of that interval is the gene's LOEUF score, 1, which puts it in group 4 of 6, group 1 being the genes least tolerant of losing a copy. Missense variants: 350 observed, 383.79 expected, observed/expected ratio (o/e) 0.91, 90% interval 0.83 to 1. Synonymous variants: 161 observed, 163.65 expected, observed/expected ratio (o/e) 0.98, 90% interval 0.87 to 1.12.
Gene-disease validity (ClinGen):
ClinGen rates the evidence that SRD5A3 causes each of these diseases.
SRD5A3-congenital disorder of glycosylation (autosomal recessive): Definitive.
Homologues: Orthologues: chimpanzee SRD5A3 (100% identical), dog SRD5A3 (91% identical), guinea pig SRD5A3 (84% identical), rat Srd5a3 (82% identical), mouse Srd5a3 (81% identical), macaque SRD5A3 (81% identical), tropical clawed frog srd5a3 (54% identical), zebrafish srd5a3 (42% identical), Drosophila melanogaster CG7840 (26% identical), Caenorhabditis elegans B0024.13 (23% identical).
Diseases named in the same sentence as SRD5A3 in open-access papers:
SRD5A3 is named in the same sentence as 67 diseases in open-access papers, as found by Europe PMC text mining. Sharing a sentence is not in itself a finding about the gene and the disease. The quoted sentences say what the papers report.
prostate carcinoma (16 papers, 2011 to 2025). A carcinoma that arises from epithelial cells of the prostate gland. "Many studies have reported high expression of SRD5A3 in liver, breast, endometrial, and prostate cancers, and its high expression is associated with poor prognosis, which is a cancer-promoting effect and is involved in the proliferation of cancer cells." (PMID 40397909, 2025). "It is worth noting that the eGene SRD5A3 was reported as a risk gene for prostate cancer in our transcriptome-wide association study (TWAS) analysis using two distinct prostate cancer GWAS studies." (PMID 38066556, 2023). "SRD5A3 is overexpressed in prostate cancer, and several studies have proposed an association between prostate cancer and AGA." (PMID 33920399, 2021). "The recently described type III (SRD5A3) was originally identified in prostate cancer tissue and acts as a polyprenol reductase involved in the N-linked glycosylation of proteins." (PMID 22257483, 2012). "Except for the oncogene role in prostate cancer, recent researchers suggested that SRD5A3 may play an important role in protein N-linked glycosylation." (PMID 36159555, 2022). "For example, SRD5A3 is overexpressed in hepatocellular carcinoma, breast carcinoma, endometrial carcinoma, and prostate carcinoma, and patients with SRD5A3 high expression suggest a poor prognosis." (PMID 40397909, 2025). "After various treatment regimes, fluorescent microscopy was performed to visualize the subcellular localization of immunofluorescence-tagged SRD5A1 and SRD5A3 in the prostate cancer PC-3 and LNCap cell lines." (PMID 37152995, 2023). "The overexpression of Srd5a3 increases the levels of DHT, which causes hair loss and prostate diseases including benign prostatic hyperplasia and prostate cancer." (PMID 35518925, 2022). "SRD5A3 was originally identified in hormone-refractory prostate tissue by genome-wide gene expression profiles and SRD5A3 inhibition also suppressed the proliferation of prostate cancer cells." (PMID 36159555, 2022). "Knockdown of SRD5A3 expression in prostate cancer cells resulted in a significant decrease in DHT production and a drastic reduction in cell viability." (PMID 34692502, 2021). "Our qRT-PCR analysis showed that DHT treatment resulted in an increased level of SRD5A1 mRNA, whereas it led to decreased levels of SRD5A2 and SRD5A3 mRNA in LNCaP prostate cancer cells." (PMID 22194926, 2011). "Our identification of an nARE in the promoter of SRD5A3 allows us to further investigate the transition from positive to negative regulation of SRD5A3 expression that occurs with prostate cancer progression over time." (PMID 22194926, 2011). "Also, in both human prostate cancer (DU-145) and HFDPC cells, the ethanolic Buebang 3 CMU extract (Et-BB3-CMU) suppressed SRD5A1, SRD5A2, and SRD5A3 expression—key pathways in hair loss—by 2-fold and 1.5-fold more than minoxidil and finasteride, respectively." (PMID 39519997, 2024). "SRD5A1 and SRD5A3 were the primary isozymes in the prostate cancer cells, and suppression of SRD5A1 and SRD5A3 protein levels was reported to be a promising alternative therapy to block the AR signaling pathway and inhibit the growth of malignant prostate tumors." (PMID 37152995, 2023). "SRD5A3 is considered to be a target of prostate cancer treatment." (PMID 34035809, 2021). "Furthermore, to our knowledge, this is the first publication of evidence that SRD5A3 has at least one nARE and that AR directly binds to this nARE region, demonstrating that SRD5A3 is under transcription inhibition by AR in prostate cancer cells." (PMID 22194926, 2011). "Knockdown of SRD5A3 expression also reduced the growth and viability of prostate cancer cells." (PMID 22194926, 2011). "Therefore, the role of SRD5A3 in both prostate cancer progression and prevention is worth further investigation." (PMID 22194926, 2011).
prostate carcinoma (continued). "Indeed, knockdown of SRD5A3 expression could inhibit the growth and cell proliferation of prostate cancer and hepatocellular carcinoma cells." (PMID 35739271, 2022). "Silencing SRD5A3 was demonstrated to decrease DHT production in prostate cancer cells and reduce cell viability, indicating its tumor-promoting activity in prostate cancer." (PMID 39680264, 2024). "In human prostate cancer cells (DU-145) and HFDPC cells, the SFE-4 extract significantly decreased the expression of SRD5A1, SRD5A2, and SRD5A3, an essential pathway involved in AGA." (PMID 38002174, 2023). "Type I and type III 5α-reductase (SRD5A1 and SRD5A3) were discovered to be correlated with DHT generation and AR activation in malignant prostate tumors, while type II (SRD5A2) is primarily expressed in normal prostate tissues." (PMID 37152995, 2023). "AR is recruited to a negative androgen response element on the promoter of SRD5A3 and the different expression levels of 5α-reductase isoenzymes affect patient response to 5α-reductase inhibitors in prostate cancer." (PMID 39680264, 2024). "Type I and III of SRD5A coexist in prostate cancer cells to boost the AR pathway and support prostate cancer initiation and progression, thus downregulating either SRD5A1 or SRD5A3 may restrict the AR pathway and further inhibit the growth of prostate cancer cells." (PMID 37152995, 2023).
hepatocellular carcinoma (7 papers, 2020 to 2025). A malignant tumor that arises from hepatocytes. "In a hepatocellular carcinoma (HCC) study, researchers demonstrated that CSPG4P12, combining 5 other genes (BX537318.1, TMEM147, AC015908.3, CEBPZOS, and SRD5A3), served as the signature for prognostic evaluation of HCC." (PMID 38877481, 2024).
breast carcinoma (6 papers, 2021 to 2025). "Loss or overexpression of SRD5A3 is closely related to breast cancer and loss of glycosylation function." (PMID 37305349, 2022). "Copy number deletion and downregulated expression of ACSL1 and upregulation of SRD5A3 both were observed in breast cancers." (PMID 35739271, 2022). "The study aimed to compare the Steroid 5 alpha-reductase 3 (SRD5A3) expression levels in breast cancer (BC) and normal tissues, to investigate the prognostic value of SRD5A3 mRNA expression in BC patients and to identify the SRD5A3-related signaling pathways using bioinformatics approaches." (PMID 34465365, 2021).
coloboma (4 papers, 2014 to 2021). An abnormality in which a part of a structure in one or both eyes is missing. "Colobomas have been described in four other families each carrying different mutations in the SRD5A3 gene." (PMID 34925443, 2021). "These include: connective tissue involvement in ATP6AP1-CDG, midline malformations in PGM1-CDG, chronic diarrhoea in MPI-CDG, inverted nipples and abnormal fat distribution in PMM2-CDG, cataract/coloboma in SRD5A3-CDG, cerebellar hypoplasia in PMM2-CDG and SRD5A3-CDG." (PMID 33407696, 2021). "Congenital colobomas, although extremely rare in CDG syndromes, are suggestive of SRD5A3-CDG whenever present, and glaucoma is described in SRD5A3-CDG but not other types of CDG." (PMID 24433453, 2014).
cataract (3 papers, 2015 to 2022). Partial or complete opacity of the crystalline lens of one or both eyes that decreases visual acuity and eventually results in blindness. "Ocular findings by CDG due to the SRD5A3 gene variant have been reported by microphthalmia, cataract, chorioretinal coloboma, glaucoma, optic nerve hypoplasia/atrophy, and nystagmus." (PMID 35205402, 2022). "Unlike other CDG types, cataracts (ocular findings) have only been reported in ALG8-CDG, ALG12-CDG, other subtypes in early LLO synthesis (like SRD5A3-CDG) and some unclassified CDG." (PMID 26066342, 2015).
Intellectual disability (3 papers, 2021 to 2023). "SRD5A3-CDG is also characterized by variable neurological symptoms including intellectual disability, cerebellar abnormalities, and hypotonia." (PMID 34925443, 2021). "SRD5A3-CDG is also characterized by variable neurological symptoms including intellectual disability, ataxia, and hypotonia." (PMID 34925443, 2021). "A similar approach was used to identify the causal gene in other UAE families, such as METTL23 in a large inbred UAE family of Yemeni origin with intellectual disability and SRD5A3 in another UAE family of Baluchi origin with a new type of glycosylation disorder." (PMID 37214420, 2023). "However, SRD5A3-CDG is a multi-systemic disorder also characterized by variable neurological symptoms including intellectual disability, hypotonia, and ataxia." (PMID 34925443, 2021).
alopecia (2 papers, 2025 to 2026). Hair loss usually from the scalp. "Here, we analyzed the gene expression of the two main 5α-reductases associated with hair loss, SRD5A1 and SRD5A3." (PMID 40286110, 2025).
congenital disorder of glycosylation (2 papers, 2026). Congenital disorder of glycosylation (CDG) is a fast growing group of inborn errors of metabolism characterized by defective activity of enzymes that participate in glycosylation (modification of proteins and other macromolecules by adding and processing of oligosaccharide side chains). "The identification of SRD5A3, a causative gene for congenital disorders of glycosylation (CDGs), together with its yeast ortholog DFG10, established the prevailing model that dolichol is synthesized from polyprenol in a single step." (PMID 42201967, 2026). "We report a very rare autosomal recessive metabolic disorder in monozygotic twin sisters caused by the steroid 5a-reductase type 3 (SRD5A3) gene defect, a subtype of congenital disorder of glycosylation (CDG)." (PMID 41769439, 2026).
Kahrizi syndrome (2 papers, 2014 to 2016). An autosomal recessive disease that is characterized by mental retardation, cataracts, coloboma, kyphosis, and coarse facial features and has material basis in mutation in the SRD5A3 gene. "It was later shown to result from a homozygous truncating SRD5A3 mutation, indicating that SRD5A3-CDG and Kahrizi syndrome are allelic disorders." (PMID 24433453, 2014).
metastatic prostate carcinoma (2 papers, 2021 to 2023). A carcinoma that arises from the prostate gland and has spread to other anatomic sites. "The down-regulated expression level of AKR1C2 combined with upregulated expression of SRD5A1 and SRD5A3 may lead to the high levels of DHT either in primary or metastatic prostate cancer." (PMID 36701414, 2023).
Nystagmus (2 papers, 2021 to 2022). Rhythmic, involuntary oscillations of one or both eyes related to abnormality in fixation, conjugate gaze, or vestibular mechanisms. "Using our cohort, and those described in the literature, we can suggest that nystagmus followed by the development of early retinal dystrophy and visual impairment forms part of the natural disease history in SRD5A3-CDG patients." (PMID 34925443, 2021).
Retinal dystrophy (2 papers, 2021 to 2022). Retinal dystrophy is an abnormality of the retina associated with a hereditary process. "The SRD5A3 gene variant causes early-onset retinal dystrophy, in addition to optic nerve complications." (PMID 35205402, 2022). "SRD5A3-CDG and other CDG subtypes in the early dolichol pathway should be considered as a cause of early-onset retinal dystrophy, particularly if patients present with multisystem disease." (PMID 34925443, 2021).
B-cell non-Hodgkin lymphoma (1 paper, 2025). The most common type of non-Hodgkin lymphoma. "However, The role of SRD5A3 in B-cell non-Hodgkin lymphoma (B-NHL) and its mechanism are unknown." (PMID 40397909, 2025).
bladder (1 paper, 2024). "Our findings provide a better knowledge of the epitranscriptional regulation mechanisms of SRD5A3 expression and the biological and epigenetic importance of m6A reader IGF2BP3 in bladder tumorigenesis." (PMID 39680264, 2024). "Therefore, we concluded that SRD5A3 and IGF2BP3 play oncogenic roles in bladder tumorigenesis, and IGF2BP3 directly interacts with SRD5A3 mRNA and increases its stability during cisplatin resistance development in bladder cancer." (PMID 39680264, 2024).
bladder cancer (1 paper, 2024). "In this study, we revealed the regulation of SRD5A3 mRNA expression mediated by m6A reader IGF2BP3 during cisplatin resistance development in bladder cancer." (PMID 39680264, 2024). "Collectively, the study unveils that IGF2BP3-mediated SRD5A3 m6A modification facilitates bladder cancer progression and induces CDDP resistance, providing rational therapeutic targets for bladder cancer patients." (PMID 39680264, 2024). "The study identified SRD5A3 as an oncogene for bladder cancer and stabilized by a m6A reader, IGF2BP3, to sustain CDDP resistance." (PMID 39680264, 2024). "Our results revealed that the expression of SRD5A3 was elevated in human bladder cancer tissues and cell lines, and this elevation was more evident in CDDP-resistant T24 and 5637 cells." (PMID 39680264, 2024). "For clinical validation of SRD5A3 in bladder cancer, we performed qRT-PCR and immunoblotting analysis in these tissue samples to verify immunohistochemical staining results again." (PMID 39680264, 2024). "To determine whether SRD5A3 has the ability to affect the killing effect of CDDP on bladder cancer cells in vivo, we injected transfected or untransfected T24R cells subcutaneously into mice to construct subcutaneous implantation model." (PMID 39680264, 2024). "Our results revealed an upregulation of SRD5A3 in bladder cancer tissues and SRD5A3 knockdown could reduce bladder cancer cell proliferation, prevent CDDP resistance, induce cell apoptosis, and inhibit bladder tumorigenesis in mice." (PMID 39680264, 2024). "To examine the regulatory role of m6A modification in SRD5A3 expression during cisplatin resistance development in bladder cancer, we performed MeRIP-qPCR and found an increased m6A levels of SRD5A3 in T24R and 5637R cells compared to their wild-type counterparts." (PMID 39680264, 2024). "As analyzing results of the GSE231835 dataset showing upregulated SRD5A3 in CDDP-resistant T24 cells compared to parental T24 cells, we sought to characterize the relationship between SRD5A3 and CDDP resistance in bladder cancer." (PMID 39680264, 2024). "In this study, we sought to demonstrate the oncogenic role of SRD5A3 and its interplay with IGF2BP3 via a m6A-dependent manner in bladder cancer and CDDP resistance." (PMID 39680264, 2024). "It was also showed SRD5A3 was lowly expressed at the mRNA and protein levels in standard SV-HUC-1 cells compared to bladder cancer cells (T24 and 5637)." (PMID 39680264, 2024). "The following cellular and animal studies demonstrated that SRD5A3 and IGF2BP3 knockdown effectively reduced bladder cancer cell proliferation, prevented chemoresistance, and induced cell apoptosis." (PMID 39680264, 2024). "In conclusion, the study provides compelling in vitro and in vivo evidences proving the m6A modification machinery between SRD5A3 and IGF2BP3 in bladder cancer." (PMID 39680264, 2024). "Results showed that SRD5A3 exhibited a higher expression at the mRNA level in the tumor tissues of 30 bladder cancer patients than the matched adjacent non-tumor bladder tissues, so did at the protein level." (PMID 39680264, 2024). "SRD5A3 stood out as one of genes upregulated in CDDP-resistant T24 cells compared to parental T24 cells, with log2FoldChange = 1.41 and P < 0.0001, which provoked us to characterize the role of SRD5A3 in the context of bladder cancer." (PMID 39680264, 2024). "Notably, SRD5A3 and IGF2BP3 were highly expressed in bladder cancer tissues and cell lines." (PMID 39680264, 2024).
bladder urothelial carcinoma (1 paper, 2024). "Furthermore, the UALCAN database showed that the transcript level of SRD5A3 was higher in the primary bladder urothelial carcinoma (n = 408) than that in the normal samples (n = 19) (P = 0.0001)." (PMID 39680264, 2024).
colorectal cancer (1 paper, 2021). A primary or metastatic malignant neoplasm that affects the colon or rectum. "Only two studies reported that low SRD5A3 expression was observed in colorectal cancer." (PMID 34465365, 2021).
congenital muscular dystrophy (1 paper, 2011). A muscular dystrophy that is characterized by diminished muscle tone (hypotonia), progressive muscle weakness and degeneration (atrophy), abnormally fixed joints, spinal rigidity, and delays in reaching motor milestones such as sitting or standing unassisted. "Also, the recently described polyprenol reductase SRD5A3-CDG (MIM 612379) does not show signs of a congenital muscular dystrophy." (PMID 22242004, 2011).
Dystonia (1 paper, 2021). An abnormally increased muscular tone that causes fixed abnormal postures. "Dystonia might, therefore, be an additional neurological feature that needs to be evaluated in SRD5A3-CDG patients." (PMID 34925443, 2021).
dystroglycanopathies (1 paper, 2021). "The cerebellum is commonly affected in PMM2-CDG, dystroglycanopathies, and SRD5A3-CDG, while the course of cerebellar ataxia is not progressive." (PMID 34540767, 2021).